NF1 (neurofibromin 1)
Diseases named in the same sentence as NF1 in open-access papers (continued):
Sharing a sentence is not in itself a finding about the gene and the disease.
cyst (1 paper, 2025). A sac-like closed membranous structure that may be empty or contain fluid or amorphous material. "Mutations in the PKD1/PKD2, which are responsible for ADPKD, affect intracellular signaling, including the mammalian target of the rapamycin (mTOR) pathway, leading to cyst formation and progression, while NF1 mutations overactivate the Ras proteins." (PMID 40051696, 2025). "We described a case of ADPKD and NF1 with early-onset cyst growth and progressive renal dysfunction." (PMID 40051696, 2025). "His disease progression was more severe than that of his father with ADPKD alone, suggesting NF1 may have accelerated cyst enlargement." (PMID 40051696, 2025). "We found that renal dysfunction and cyst enlargement occurred earlier in patients with both ADPKD and NF1 than in fathers with ADPKD alone." (PMID 40051696, 2025). "However, the rapid cyst growth suggests NF1 may have contributed to mTOR activation by ADPKD." (PMID 40051696, 2025). "As neurofibromin is expressed in tubules and both neurofibromin and PC1 regulate Ras signaling, we speculate that NF1 may enhance ADPKD-driven mTOR signaling, potentially accelerating cyst enlargement." (PMID 40051696, 2025).
delirium (1 paper, 2018). A disorder characterized by confusion; inattentiveness; disorientation; illusions; hallucinations; agitation; and in some instances autonomic nervous system overactivity. "There were markers in both serum and CSF that differed between the affected and non-affected patients (SCI; IL6, GFAP, CSPG4, delirium; TR4, EZH2, hallucinations; NF1)." (PMID 30367354, 2018).
diabetic neuropathy (1 paper, 2025). A chronic, pathological complication associated with diabetes mellitus, where nerve damages are incurred due to diabetic microvascular injury involving small blood vessels that supply these nerves, resulting in peripheral and/or autonomic nerve dysfunction. "Similarly, NF-1 reduces oxidative stress and apoptosis in neuronal cells under high-glucose conditions, indicating its potential in diabetic neuropathy." (PMID 40903459, 2025).
duodenal tumor (1 paper, 2025). "Next-generation sequencing (NGS) of the duodenal tumor sample identified an NF1 mutation, with no other gene mutations clearly associated with malignant transformation." (PMID 41001300, 2025).
Dyskinesia (1 paper, 2018). A movement disorder which consists of effects including diminished voluntary movements and the presence of involuntary movements. "To explore the role of Nf1 in dyskinesia, we studied the development of LID in hemiparkinsonian/6-OHDA-lesioned mice by scoring axial dystonia and forelimb and orofacial dyskinesias in Nf1+/− and their WT littermates." (PMID 30337665, 2018). "Since spontaneous locomotor activity and motor coordination are normal in the Nf1+/− mice, results of dyskinesia experiments are not due to motor impairment, but rather to the modification of Nf1-related molecular pathways." (PMID 30337665, 2018).
Encephalopathy (1 paper, 2023). Encephalopathy is a term that means brain disease, damage, or malfunction. "For example, the mRNA expression trend of NF1, RAB14, ADCY5, and RAPGEF3 in the blood is the same as that in encephalopathy, suggesting that the purpose of assessing brain state can be achieved by detecting blood-related indicators." (PMID 36923118, 2023).
endometrial tumors (1 paper, 2022). "Similarly, in endometrial tumors, KRAS G13D mutated tumors showed a higher prevalence of NF1 and PTEN alterations compared to KRAS G12D (NF1: 14.0% vs. 6.1%, FDR p = 0.005; PTEN: 70.6% vs. 55.1%, p = 0.0006, respectively)." (PMID 36494601, 2022).
epidermolytic ichthyosis (1 paper, 2023). A rare keratinopathic ichthyosis (KPI), that is characterized by a blistering phenotype at birth which progressively becomes hyperkeratotic. "First, it is well-established that mosaic mutations can be passed on to offspring as germline heterozygous disease, for example, epidermal naevi with keratin 1 gene K1 and keratin 10 gene K10 mutations passed on as epidermolytic ichthyosis or mosaic NF1 being passed down as germline NF1." (PMID 36566878, 2023).
Fabry disease (1 paper, 2025). Fabry disease (FD) is a progressive, inherited, multisystemic lysosomal storage disease characterized by specific neurological, cutaneous, renal, cardiovascular, cochleo-vestibular and cerebrovascular manifestations. "In the other 13 patients, informative SNPs were found only in the 5’ flanking region (1 patient each with hemophilia A and Fabry disease) or the 3’ flanking region (6 patients with NF1 and 5 patients with Kennedy disease)." (PMID 40710390, 2025).
familial amyotrophic lateral sclerosis (1 paper, 2010). An instance of amyotrophic lateral sclerosis that is caused by an inherited modification of the individual's genome. "SOD1 and NF1 and their homologues have appeared in our gene ontology search as linked with several types of myelopathies and familial amyotrophic lateral sclerosis." (PMID 21152067, 2010).
familial atypical multiple mole melanoma syndrome (1 paper, 2025). "Germline 9p21.3 deletions involving the contiguous CDKN2A/CDKN2B/ANRIL region exhibit cancer predisposition syndrome with characteristics overlapping NF1, familial atypical multiple mole melanoma syndrome (FAMMM), and Li–Fraumeni syndrome (LFS)." (PMID 40046620, 2025).
fibrous hamartoma (1 paper, 2019). "In pathological detection of pseudarthrosis tissue from NF1 CPT patients, highly cellular fibrocartilage (also known as fibrous hamartoma) was found." (PMID 31533797, 2019).
freckles (1 paper, 2022). Disorders of increased melanin pigmentation that develop without preceding inflammatory disease. "In families with an autosomal dominant phenotype of CALM with or without freckles but without other NF1-associated disease features or a pathogenic NF1 gene variant, 19% have a mutation in the SPRED1 gene." (PMID 34928431, 2022).
gallbladder cancer (1 paper, 2023). "A comprehensive analysis of our data revealed that NF1 protein could affect the stabilization and ubiquitination of YAP1, resulting in gallbladder cancer progression." (PMID 37147639, 2023).
gonorrhea (1 paper, 2022). A common sexually transmitted bacterial infection caused by Neisseria gonorrhoeae. "The Nf1-MDA phage contains a meningococcal disease-associated (MDA) island, the presence of which correlates with hyperinvasive forms of gonorrhea in adults." (PMID 36555284, 2022).
Graves disease (1 paper, 2017). Graves' disease is an autoimmune disorder that leads to overactivity of the thyroid gland (hyperthyroidism).It is caused by an abnormal immune system response that causes the thyroid gland to produce too much thyroid hormones. "To date, three patients with NF1 have been diagnosed with Graves’ disease." (PMID 28552839, 2017).
growth disorders (1 paper, 2023). "All these variants were identified in genes already associated with growth disorders: PROKR2 (N = 2), PTPN11 (N = 6), ANKRD11 (N = 1), NPR2 (N = 1), NF1 (N = 1), ACAN (N = 1), GH1 (N = 1), FBN1 (N = 1), COMP (N = 1), IGF1R (N = 1), ARID1A (N = 1), and CASR (N = 1)." (PMID 37605180, 2023).
heart tumors (1 paper, 2024). "Mutations were found in Arid1a, Setd2, Nf1 and Egfr in all cardiac tumors and in Pdgfra for eight of the tumors." (PMID 38232086, 2024).
Hematochezia (1 paper, 2024). The passage of fresh (red) blood per anus, usually in or with stools. "A 42-year-old male with NF1 presented with severe hematochezia and underwent initial non-contrast CT, which was negative for abnormalities." (PMID 39835036, 2024).
Hyperparathyroidism-jaw tumor syndrome (1 paper, 2017). "First, we examined the ExAC cohort for variants previously reported as disease-causing in six genes associated with penetrant monogenic disorders (i.e., FHH, MEN1 and MEN2, hyperparathyroidism-jaw tumor syndrome, NF1, and VHL)." (PMID 29308445, 2017).
hypogonadism (1 paper, 2025). A disorder characterized by decreased function of the gonads. "NYNRIN, TUFM, and SH2B1 were uniquely identified by colocalization analysis of hypogonadism, while NF1, PABPC4, and SHROOM3 were uniquely identified through colocalization analysis of total testosterone." (PMID 40316537, 2025).
hypospadias (1 paper, 2023). Hypospadias is the displacement of the urethral meatus on the ventrum of the penis. "Hypospadias was documented in one other live birth and considered unrelated to NF1." (PMID 37337089, 2023).
hypoxic-ischemic encephalopathy (1 paper, 2018). "Seven forms were identified someway related to NF1, two of which were associated to 17q11.2 microdeletion and hypoxic-ischemic encephalopathy." (PMID 29566708, 2018).
invasive carcinoma (1 paper, 2015). A carcinoma that is not confined to the epithelium, and has spread to the surrounding stroma. "The NF1 deletion was present in 1.2% of the primary invasive carcinoma in the fallopian tube and 7.9% of the biopsy from the adjacent left ovarian metastasis." (PMID 25710373, 2015).
lactic acidosis (1 paper, 2017). Metabolic acidosis characterized by the accumulation of lactate in the body. "For example, genes such as TXNIP and ARRDC4, which are both indicative of lactic acidosis, correlate with better clinical outcomes, and contribute to predicting tumors with intact NF1 signaling." (PMID 28166733, 2017).
liver neoplasm (1 paper, 2022). Tumors or cancers of the LIVER. "In line with this article, we have found that the most representative pathogenic genomic variant of NF1 was the c.2568C>G, which has been described only in liver neoplasm and affects the MAPK signaling pathway, whose role is acknowledged in tumor cell proliferation." (PMID 36289852, 2022).
lung disease (1 paper, 2025). "This combination has been considered a hallmark of NF1-associated lung disease, although it is not pathognomonic of the condition." (PMID 39912006, 2025).
mantle zone lymphoma (1 paper, 2020). "In contrast, virus-positive MCC was identified in a patient with mantle zone lymphoma having been treated with Rituximab for 3 years and another with germline mutations in NF1 and GATA2." (PMID 32188490, 2020).
mediastinal schwannoma (1 paper, 2025). A schwannoma that arises from the posterior mediastinum. "We present a case of a giant mediastinal schwannoma in NF-1 that required differentiation from an MPNST." (PMID 40861330, 2025).
mediastinal tumors (1 paper, 2013). "Of the six mediastinal tumors, all were conventional MPNSTs and 2 were associated with NF1 (33%)." (PMID 24133387, 2013).
megalencephaly (1 paper, 2021). A congenital abnormality in which the occipitofrontal circumference is greater than two standard deviations above the mean for a given age. "It is hypothesized that the increases in total white matter volume, total brain volume, and megalencephaly that occur in NF1 are related to the dysregulation of oligodendrocytes, the myelin-producing cells in the central nervous system." (PMID 34727946, 2021).
Merkel cell carcinomas (1 paper, 2016). "Importantly, aberrations in the PI3K/AKT/mTOR pathway (AKT2, FBXW7, NF1, PIK3CA, PIK3R1, PTEN or RICTOR) were also commonly seen in Merkel cell carcinomas (9/17 [53%])." (PMID 26981779, 2016).
metabolic bone disorder (1 paper, 2013). A group of disorders that affect the bones secondary to increased levels of minerals or deficient levels of minerals such as calcium, magnesium, phosphorus, and vitamin D. Representative examples are osteomalacia, osteoporosis, and Paget disease. "The loss of neurofibromin 1 function (the mechanism inherent to NF-1 pathophysiology) can cause generalized metabolic bone disorders." (PMID 23936704, 2013).
metabolic myopathy (1 paper, 2021). A group of rare inherited disorders characterized by a deficiency of enzymes that are involved in metabolic pathways that affect muscles. "NF1 has shown features of a metabolic myopathy, and histological staining of quadriceps muscle in Nf1Prx1−/− revealed an accumulation of intramyocellular lipid." (PMID 34935315, 2021).
metastasis (1 paper, 2011). The spread or migration of cancer cells from one part of the body (where they first appeared) to another. "Alterations of the Ras/MAPK pathway have been observed in disease models of Paget's bone disease, bone metastasis, and Neurofibromatosis type 1 (NF1)." (PMID 21961044, 2011).
microcephalic osteodysplastic primordial dwarfism type II (1 paper, 2015). A form of microcephalic primordial dwarfism (MPD) characterized by severe pre- and postnatal growth retardation, with marked microcephaly in proportion to body size, skeletal dysplasia, abnormal dentition, insulin resistance, and increased risk for cerebrovascular disease. "Patients with disorders such as Down syndrome, sickle cell disease, neurofibromatosis type 1 (NF-1), and microcephalic osteodysplastic primordial dwarfism type II (MOPD II) have a higher incidence of MM angiopathy, collectively termed MM syndrome (MMS)." (PMID 26530418, 2015).
minimal change disease (1 paper, 2025). "In the context of NF1, where the loss of neurofibromin results in constitutive Ras activation, this may lower the threshold for podocyte injury and contribute to the development of minimal change disease." (PMID 40625468, 2025).
mucinous tumors (1 paper, 2012). "These include: FH, GMPS, PIK3CA, EIF4A2, ZNF384, and SS18L1 (amplifications in serous tumors); TET2, FGFR10P, NF1, ERBB2, and SH3GL1 (deletions in serous tumors) and ERBB2 (amplifications in mucinous tumors)." (PMID 23078675, 2012).
multiple glomus tumors (1 paper, 2018). "The case report on herein provides further support for the notion that NF1 has an associated risk for multiple glomus tumors." (PMID 30336779, 2018).
multiple sclerosis (1 paper, 2024). A progressive autoimmune disorder affecting the central nervous system resulting in demyelination. "Interestingly, a relation between multiple sclerosis and NF1 has been suggested in the literature." (PMID 39795595, 2024).
myelodysplastic/myeloproliferative syndrome (1 paper, 2023). "Although NF1 mutations are risk factors for JMML, the presence of monosomy of chromosome 5, and low levels of fetal hemoglobin (HbF), were more indicative of secondary myelodysplastic/myeloproliferative syndrome (MDS/MPS)." (PMID 37761810, 2023).
myocardial ischemia (1 paper, 2025). A disorder of cardiac function caused by insufficient blood flow to the muscle tissue of the heart. "Enhanced Myh7 and Nf1 were found in the heart of myocardial ischemia rat model in compression with the normal group." (PMID 40271502, 2025).
nasopharyngeal tumor (1 paper, 2022). "Of note, this non-NF-1 patient was treated 11 years before PBSPT for a nasopharyngeal tumor with 70 Gy." (PMID 35832560, 2022).
nephrotic syndrome (1 paper, 2025). A collection of symptoms that include severe edema, proteinuria, and hypoalbuminemia; it is indicative of renal dysfunction. "This case underscores the importance of considering renal pathology in NF1 patients with nephrotic syndrome and raises the possibility of a biologically plausible link between NF1-related dysregulation of the Ras signaling pathway and podocyte injury as observed in MCD." (PMID 40625468, 2025). "Our patient is only the second case of MCD associated with NF1 and, more importantly, the first case described in which MCD developed without a concomitantly identified tumor that could be directly implicated in a paraneoplastic mechanism for nephrotic syndrome." (PMID 40625468, 2025).
neural tube defect (1 paper, 2025). A congenital defect characterized by failure of the neural tube to close completely; this results in the presence of openings in the brain or spinal cord. "As a general rule, pregnant women should begin taking folic acid before conception to reduce the risk of neural tube defects in their children, regardless of the presence of NF1." (PMID 39860457, 2025).
neurotoxicity (1 paper, 2022). Toxicity that causes injury to the central or peripheral nervous system or damages its function. "The third module included 3 genes in Neurotoxicity (Itpr1, Trim8, Lrp1), 4 in Blood–brain barrier (Ptpn23, Claudin5, Plectin, Mmp2) and 4 in Cognitive function (Slc8a3, Srf, Nf1, Ncam1)." (PMID 35899365, 2022).
optic nerve tumor (1 paper, 2025). "At 12 weeks of age, while CBP-treated Nf1OPG mouse nerve volumes were unchanged (0.99-fold change), there was a reduction in optic nerve tumor proliferation to levels comparable to Nf1+/- mice, as measured by the percentage of Ki67+ cells, compared to untreated Nf1OPG mice." (PMID 41497446, 2025).
oral cavity cancer (1 paper, 2025). A primary or metastatic malignant neoplasm involving the oral cavity. "Comparing mutational outline of recurrent and non-recurrent cases of oral cavity cancer, aberration of NF1 gene was seen in maximum patients." (PMID 40457841, 2025).
ossifying fibroma (1 paper, 2020). A bone benign neoplasm that is located_in the mouth and results_in an overgrowth of gingival tissue due to irritation or trauma. "Molecular analysis of the NF1 gene both on blood cells and non-ossifying fibroma’s biopsy tissue allowed the detection of a novel variant within the coding region, NM_000267.3:c.2789_2791delATC(p.Tyr930_Pro931delinsSer), with loss of heterozygosity (second hit mutation) in the non-ossifying fibroma." (PMID 32393377, 2020).
ovarian endometrioid carcinoma (1 paper, 2025). "We evaluated both WES and WGS data for homozygous deletions and identified losses in multiple genes known to be altered in ovarian endometrioid carcinomas, including PTEN, NF1, ARID1A, BRCA1, and others." (PMID 40981433, 2025). "These analyses revealed several novel rearrangements that were predicted to result in in-frame protein fusions in ovarian endometrioid carcinomas, including ATAD1–PTEN, the neurofibromin genes NF1 and NF2, as well as cyclin-dependent and polo-like kinase (PLK) genes CDK7 and PLK5." (PMID 40981433, 2025). "Rearrangements involving NF1 and NF2 have been reported in other cancers and have been associated with therapeutic resistance in HGSOC but have not been previously identified in ovarian endometrioid carcinoma." (PMID 40981433, 2025).
ovarian hyperstimulation syndrome (1 paper, 2023). A complication of ovulation induction in infertility treatment. "Complications of IVF treatment (ovarian hyperstimulation syndrome and/or ovarian bleeding) were reported in two (out of 40) women with NF1 (5.0%) and in four (out of 27) women (14.8%) where the male was affected with NF1 (p = 0.21)." (PMID 37337089, 2023).
Pan (1 paper, 2021). "The subsequent analysis of Pan-Cancer TCGA dataset and Cancer Cell line Encyclopedia (CCLE) uncovered that NF1 mutations promote cancer not only by increasing Ras signaling but, also, by increasing the number of mutations that would further increase the Ras signaling." (PMID 34065786, 2021).
pinworm infection (1 paper, 2022). "To repurpose molecules potentially targeting RAS−activated cells, we screened NF1 KO AML cells using a large FDA-approved compound library and identified pyrvinium pamoate, an oral anthelminthic drug employed in pinworm infection." (PMID 35354920, 2022).
primary immunodeficiency (1 paper, 2022). "Almost half of the caregivers had a child with NF1 (48.6%), followed by a primary immunodeficiency (25.7%), cancer (20%), and then SCD (5.7%)." (PMID 35455544, 2022). "The primary medical diagnosis of patients surveyed included NF1 (36.9%), cancer (22.6%), SCD (22.5%) and a primary immunodeficiency (16.7%)." (PMID 35455544, 2022).